GABRD (gamma-aminobutyric acid type A receptor subunit delta)
Diseases named in the same sentence as GABRD in open-access papers (continued):
Sharing a sentence is not in itself a finding about the gene and the disease.
tumor (continued). "In adult IDH wild-type (WT) diffuse LGG, GABRD expression was independently associated with overall survival (OS) status and showed a moderate negative correlation with tumor-infiltrating macrophages (TIMs)." (PMID 33718116, 2020). "GABRD has also been referred to in tumors in several other studies, but many of these are based on bioinformatic data and the functional relevance of GABRD to carcinogenesis and tumor progression remains to be elucidated." (PMID 33336074, 2020). "One explanation for this disparity is that GABRD transcripts may be predominantly expressed in ACC tumor host cells, such as T-cells." (PMID 33187258, 2020). "As in vitro experiments further confirm its involvement in tumor proliferation, we postulate that GABRD could be a novel prognostic predictor for CRC that deserves further investigation." (PMID 33336074, 2020). "Additionally, the review examines the interaction between GABRD and the tumor microenvironment." (PMID 41900986, 2026). "The outcomes revealed that the levels of CD37, GABRD and ARHGAP25 were significantly elevated in the tumor cells than that in the normal cell line." (PMID 37465666, 2023). "In this study, our data demonstrated that GABRD expression was upregulated in ESCC, and its silencing can inhibit the proliferation and migration of the tumor cells." (PMID 35706026, 2022). "Meanwhile, GABRD expression was upregulated in ESCC, and its silencing can inhibit the proliferation and migration of the tumor cells." (PMID 35706026, 2022). "Taken together, these observations suggested that GABRD promoted CRC progression by enhancing cell proliferation and migration, and interacting with crucial pathways involved in tumor progression." (PMID 33336074, 2020). "Further investigation revealed increased protein expression levels of UCN in tumor tissues compared to normal tissues in CRC patients but not GABRD." (PMID 39336730, 2024). "However, the mechanisms by which GABRD and TMEM255B mediate tumor angiogenesis and proliferation remain to be elucidated." (PMID 38997406, 2024). "GABRD expression also showed a negative correlation with tumor-infiltrating macrophages, with the latter usually carrying negative prognostic value, and a specific CpG site, cg13916816, was identified as potentially influencing GABRD expression." (PMID 37511496, 2023). "Since the level of GABRD expression was shown to be connected with the grade of the tumor and the prognosis of COAD patients, we formed the hypothesis that an increased level of GABRD expression accelerates the growth of tumors." (PMID 37181811, 2023). "This notion is consistent with an unsupervised bioinformatics study of TCGA tumors (not including ACC) that identified GABRD expression as a pan-cancer marker that is overexpressed in tumor vs adjacent normal tissue." (PMID 33187258, 2020). "First, it did not provide evidence to support the oncogenic roles of GABRD in vivo, which might be quite different considering the complex interactions between tumor and the microenvironment." (PMID 33336074, 2020).
cancer (16 papers, 2015 to 2026). A tumor composed of atypical neoplastic, often pleomorphic cells that invade other tissues. "Specifically, the activation of GABRD is implicated in the initiation of key downstream signaling pathways that facilitate the proliferation, invasion, and metastasis of cancer cells." (PMID 41900986, 2026). "The γ-aminobutyric acid type A receptor d subunit (GABRD), encoded in the human chromosome 1p36 region, has yet to be fully elucidated regarding its involvement in cancers." (PMID 38099288, 2023). "This review delineates the biological characteristics of GABRD and its involvement in cancer pathophysiology." (PMID 41900986, 2026). "Specifically, Gamma‐aminobutyric acid type A receptor (GABAA receptor) subunit delta (GABRD) is found to be closely related to cancer." (PMID 40145254, 2025). "To begin, we carried out pan-cancer tests and discovered that GABRD displayed a dysregulated level in a wide variety of cancers." (PMID 37181811, 2023). "In the past, a number of studies have revealed that gamma-aminobutyric acid type A receptor subunit delta (GABRD) plays a role in the advancement of a number of different cancers." (PMID 37181811, 2023). "GABRD, a subunit of GABAA receptor subtypes, has been reported to be associated with the development of many cancers." (PMID 35967794, 2022). "The analysis for hepatocellular carcinoma found that GABRD is remarkably upregulated in each cancer stage." (PMID 34194536, 2021). "Gamma-aminobutyric acid type A receptor subunit delta (GABRD) as one of the subunits of GABAAR is found to be closely related to cancer." (PMID 34194536, 2021). "A study of pan-cancer analysis found that GABRD is one of the most upregulated genes in tumor tissue." (PMID 34194536, 2021). "UALCAN was used to analyze the expression of GABRD in different groups of age, gender, cancer stage, N stage, and histological subtype." (PMID 34194536, 2021). "In the present study, we analyzed the GABRD expression in CRCs and peritumoral normal tissues (NTs) with transcriptomic datasets from gene expression omnibus (GEO) and the cancer genome atlas (TCGA)." (PMID 33336074, 2020). "The GABA receptor family was found to be frequently downregulated in cancers, except for GABRD, which was found to be up-regulated." (PMID 31277598, 2019). "It was remarkable that GABRD stood out as the top gene in both the linear models, and with a monotonic order of expression with the cancer stage." (PMID 31277598, 2019). "There are a number of possible explanations for why many GABA subunits are downregulated, but GABRD in particular is upregulated, in cancer." (PMID 26555223, 2015). "Furthermore, it provides an analysis of the diverse roles and mechanisms attributed to GABRD across various cancer types." (PMID 41900986, 2026). "To detect whether GABRD influences cancer cell proliferation and motility abilities via CCND1, we performed a series of rescued functional experiments." (PMID 40145254, 2025). "Additionally, the study sheds light on the tumorigenic capabilities of UCN and GABRD, linking these genes to pivotal pathways known to drive cancer progression, such as MYC targets V1, MYC targets V2, and DNA repair pathways." (PMID 39336730, 2024). "Study has investigated the relationship between GABRD and cancer." (PMID 37465666, 2023). "Gamma-aminobutyric acid type A receptor subunit delta (GABRD) is a ligand-gated ion channel-type receptor that has been linked to a wide range of neurological and psychiatric disease-related symptoms as well as the progression of cancer." (PMID 37181811, 2023). "At present, there are still very few studies on GABRD in cancer." (PMID 34194536, 2021). "Research on cancer had also indicated that methylation in the c.g., 13916816 CpG site of GABRD was negatively correlated with mRNA expression and was related to the overall survival status of adult isocitrate dehydrogenase wild-type diffuse low-grade glioma patients." (PMID 33551813, 2020).
cancer (continued). "GABRD is of particular interest, as it has been identified as a pan-cancer marker." (PMID 33187258, 2020). "A co‐immunoprecipitation assay demonstrated a physical interaction between CCND1 and GABRD in AGS cells, confirming their cooperative role in cancer progression." (PMID 40145254, 2025). "A feature space of just seven biomarkers, namely ESM1, DHRS7C, OTOP3, AADACL2, LPHN3, GABRD, and LPAR1, was sufficient to optimize a RandomForest model that achieved > 98% balanced accuracy (and performant recall) of cancer vs. normal on external validation." (PMID 39484215, 2024). "A summary of the models used for building a classifier capable of discriminating between cancer and normal samples based on the expression of seven features: ESM1, DHRS7C, OTOP3, AADACL2, LPHN3, GABRD, and LPAR1." (PMID 39484215, 2024). "Our analysis of drug sensitivity revealed that the expression of CHRNA3, GABRD, GRIK3, and GRIK5 in cancer cells significantly impacted their response to chemotherapy." (PMID 38099288, 2023). "The expression of CHRNA3, GABRD, GRIK3, and GRIK5 in cancer cells significantly impacted their response to chemotherapy." (PMID 38099288, 2023). "However, the detailed biological functions and molecular mechanisms of GABRD in cancer development and progression have not been fully elucidated." (PMID 40145254, 2025).
psychiatric disease (2 papers, 2019 to 2023). "In regards to psychiatric disorders, there were strong negative correlations between oxytocin pathway genes and PAK7 and GABRD which have been associated with schizophrenia." (PMID 30737392, 2019).
infection (1 paper, 2022). The state of being infected such as from the introduction of a foreign agent such as serum, vaccine, antigenic substance or organism. "Furthermore, we found that GABRD, GABRB3, GABRE, and GABRQ, which play important roles in neuron cell growth and migration, are significantly downregulated after infection." (PMID 36147849, 2022).
GABRD also shares sentences with these, for which no sentence is quoted: neurodevelopmental disorder (3 papers); schizophrenia (3); astrocytoma (2); mood disorder (2); absence seizures (1); adenocarcinoma (1); adenoma (1); alcohol use disorders (1); Anxiety (1); anxiety disorder (1); autism (1); brain disorder (1); cholangiocarcinoma (1); cocaine addicts (1); cognitive deficits (1); Dravet syndrome (1); dyslexia (1); human papillomavirus infection (1); Intellectual disability (1); neurodegenerative disease (1); pancreatic carcinoma (1); pancreatic neoplasm (1); postpartum depression (1); psychosis (1); renal clear cell cancer (1); Rett syndrome (1); Seizure (1); Stomach (1); stomach adenocarcinoma (1); Stroke (1).
A further 1 disease shares a sentence with GABRD in 1 paper.